POSTN (periostin)
Diseases named in the same sentence as POSTN in open-access papers (continued):
Sharing a sentence is not in itself a finding about the gene and the disease.
asthma (continued). "The reason for the discrepancy between serum periostin levels and asthma severity was not clear in the current study." (PMID 30473714, 2018). "We aimed to determine the effect of sampling time during the day on serum periostin levels in adult participants with and without asthma." (PMID 28194189, 2017). "Enhanced thrombin generation is driven in asthma by a systemic inflammatory state mediated by IL-6 and to a lesser extent TNFα, however, not periostin." (PMID 28429138, 2017). "Indeed, the need for new biomarkers of inflammation in asthma has been highlighted in a recent study of an IL-13 neutralising monoclonal antibody, where measurement of airway IL-13 levels might be a more relevant biomarker than blood eosinophils and serum periostin." (PMID 28373098, 2017). "Together, these findings suggest that serum periostin is not a measure which can differentiate patients with asthma across a range of severity from a population without asthma." (PMID 28194189, 2017). "Although initially showing promise in patients with elevated blood periostin levels, replicating phase 3 studies of Lebrikizumab in severe asthma showed disparate results which has led to a lack of further clinical development for asthma." (PMID 28855973, 2017). "Furthermore, IL-13-induced periostin and DPP4 can be measured in peripheral blood and are used as biomarkers to predict the efficacy of anti-IL-13 antibodies in human asthma patients." (PMID 28775743, 2017). "This is equivalent to a mean ratio of serum periostin levels in the asthma versus non-asthma group of 1.06 (0.88–1.28)." (PMID 28194189, 2017). "Moreover, we compared the fraction ratios of monomeric periostin to total periostin in IPF with those in other periostin-high diseases: atopic dermatitis, systemic scleroderma, and asthma." (PMID 28355256, 2017). "We also estimated the time-related variation in serum periostin levels in adults without asthma, and compared the time-related variations in serum periostin with those of other markers of type-2 dominant asthma, FeNO and blood eosinophils." (PMID 28194189, 2017). "This study shows that serum periostin levels vary throughout the day in adults with and without asthma, with higher levels in the morning in both groups." (PMID 28194189, 2017). "Since ICS treatment reduces airway periostin expression and airway eosinophilia, high levels of serum periostin represent a marker of persistent airway eosinophilia despite ICS treatment in patients with uncontrolled asthma." (PMID 27965769, 2016). "Small increases in periostin levels have been reported in children with asthma compared to healthy controls at certain, but not all, ages, and moderate relationships with blood eosinophils and IgE have also been observed." (PMID 27942431, 2016). "Periostin is highly expressed by epithelial cells, is bound by αvβ3 and αvβ5 integrins, is upregulated in epithelial tumors to support adhesion and migration, and is a prognostic marker for TH2-driven asthma and lung fibrosis." (PMID 26390284, 2015). "To date, the molecular mechanisms involving periostin in relation to asthma in humans have not been fully elucidated." (PMID 25981515, 2015). "To date, cases of human asthma have not been analyzed for levels of periostin according to inflammatory phenotype." (PMID 25981515, 2015). "Further, two phase 2b trials of lebrikizumab versus placebo in moderate to severe asthma found periostin-high patients (≥50 ng/mL) experienced a 60% reduction in asthma exacerbations and a 9% forced expiratory volume in one second (FEV1) improvement compared to periostin-low patients (<50 ng/mL)." (PMID 40863432, 2025). "Cluster 1 (n = 19) was characterized by below-average age, BMI, and periostin, but showed notably higher ACT scores and better spirometric indices (pre-FEV1 and pre-FVC predicted), suggesting a cluster of patients with relatively preserved lung function and good asthma control." (PMID 41374409, 2025).
asthma (continued). "Meaningful clinical effects with anti-cytokine-based biologic therapies require carefully selected patient populations that take asthma phenotypes into account, guided by straightforward non-invasive discriminatory biomarkers, such as blood eosinophil counts, FeNO, and serum periostin." (PMID 41440490, 2025). "However, in our study, periostin was not correlated with overall lung function, indicating that it reflects the specific inflammatory aspects of asthma." (PMID 39534447, 2024). "Moreover, sputum samples from four severe asthma patients (#7 - #10) showing high sputum periostin levels measured by Assay B, but not by Assay A, showed clear bands corresponding to the cleaved product, but not the monomeric form." (PMID 36763690, 2023). "In another study omalizumab might have benefitted patients with type 2 high asthma; allergic asthma and non-allergic asthma with high levels of FeNO, IL-14, eosinophils or periostin." (PMID 40980110, 2023). "Hence, periostin may have a potential as a biomarker for ICS treatment efficacy, at least in some asthma phenotypes." (PMID 40980110, 2023). "Serum periostin has been observed in higher levels in nonsmokers than smokers with asthma." (PMID 37367073, 2023). "In this study, plasma POSTN was upregulated in patients with severe and non-severe asthma." (PMID 37130146, 2023). "Correlation of sputum eosinophils with other easily available biomarkers, such as peripheral blood eosinophils, FeNO, and serum periostin) may be useful for asthma endotyping when the induced sputum technique is not available." (PMID 37511786, 2023). "In a real-life study, it was shown that serum periostin was not related to the degree of asthma control in children, remaining unclear as to whether it could have a predictive value in identifying SA in the pediatric population." (PMID 37762787, 2023). "Th2-high asthma has three specific differentially expressed transcriptomic profiles, namely, periostin (POSTN), chloride channel regulator 1 (CLCA1), and serpin peptidase inhibitor, clade B, member 2 (SERPINB2), among which POSTN was found to be a more reliable surrogate marker for Th2-high asthma." (PMID 35406434, 2022). "Unfortunately, the low periostin level in patients with mild asthma and the lack of differences between asthmatic subjects and controls indicate that EBC periostin may not be useful as an asthma biomarker in this group." (PMID 35327702, 2022). "Additionally, in the bronchial epithelium of asthma, only females expressed higher levels of POSTN mRNA (males did not) compared to healthy controls." (PMID 34439751, 2021). "Periostin (not measured in the AD studies presented here) ranged from 56.20 to 56.95 ng/mL in EoE patients to 69.70 to 71.00 ng/mL and 99.60 to 104.00 ng/mL in asthma and CRSwNP patients, respectively." (PMID 34037993, 2021). "Furthermore, asthma patients with persistent airflow limitation were characterized by elevated type-2 (T2) inflammatory biomarkers, such as blood and BAL eosinophilia, and serum periostin when comparing the remaining asthmatics." (PMID 34204767, 2021). "The serum level of periostin is a good indicator for the efficiency of the anti-IL-13 antibody lebrikizumab in the treatment of steroid-resistant asthma but may not be the ideal predictor for the Th2hi phenotype." (PMID 34512647, 2021). "Indeed, the association between sputum periostin levels and the number of eosinophils in NPs tends to be significant when confined to CRS patients without asthma." (PMID 32015784, 2020). "Positive correlation between AREG and periostin might augment the role of neutrophils in non-eosinophilic severe asthma." (PMID 33195308, 2020). "However, the influence of smoking on sputum periostin levels has not been confirmed yet; one study of poorly-controlled asthma showed similar periostin levels between never smokers and past smokers." (PMID 32015784, 2020).
asthma (continued). "Many studies revealed the periostin as a significant marker to identify tissue eosinophilia, but our research data suggest that periostin alone is not suitable to identify asthma severity because of similar possible corticosteroid-affected periostin levels in SNEA and steroid-free AA patient groups." (PMID 31438916, 2019). "The stability of serum periostin over disease progression in adults with asthma (without seasonal effect) and in children between 4 and 11 years of age, supports its use as a biomarker for type 2-high asthma." (PMID 30598830, 2018). "Among the cytokines examined, asthma patients carrying the −1508G allele showed significantly higher serum MPO levels (150.91 ± 94.13 versus 108.26 ± 79.5 mg/L, P = 0.027) and serum periostin level than those of noncarrier asthma patients (91.83 ± 50.85 versus 71.07 ± 33.62 ng/mL, P = 0.016)." (PMID 28659663, 2017). "Finally, there is only a significant effect for disease for POSTN, which was upregulated in severe asthma, but did not appear to be affected by lung region." (PMID 28045928, 2017). "Asthma is a chronic inflammatory disease characterised by airway hyperreactivity (AHR), type-2 inflammation, and airway remodelling, which includes mucous cell hyperplasia, airway smooth muscle (ASM) growth, and the deposition of matricellular proteins (e.g. periostin)." (PMID 28539639, 2017). "Serum periostin was measured at 2-h intervals from 0800 to 1800 h in 16 adult participants with stable asthma prescribed inhaled corticosteroid and long-acting beta-agonist therapy, and in 16 otherwise healthy participants without asthma." (PMID 28194189, 2017). "Other asthma medications and co-morbidities had no impact on periostin concentration." (PMID 28429138, 2017). "Sputum periostin similarly lacked the rigor to be an adequate biomarker to detect eosinophilic asthma in adults with poorly-controlled asthma being neither sensitive nor specific and has the added disadvantage of not being easily accessible in clinical practice." (PMID 27130294, 2016). "We should also remember that periostin is not specific to asthma or the airway epithelium." (PMID 26430389, 2015). "Periostin is an ECM protein upregulated by T helper cell type 2 (Th2) cytokines in bronchial epithelial cells and lung fibroblasts and is deposited in patients with asthma and atopic dermatitis, as well as in animal models of asthma and allergic skin inflammation." (PMID 23554594, 2013). "Also, measuring serum periostin with a common commercial ELISA kit is neither complicated nor expensive; hence, it could be performed routinely in selected patients in severe asthma units." (PMID 37744693, 2023). "Serum periostin showed significant time-of-day variation in both asthma and healthy individuals; however, during the clinical working day (10:00 h and 16:00 h), serum periostin levels remained stable in asthma (and healthy people) and so would be unlikely to influence asthma management decisions." (PMID 37404842, 2023). "Furthermore, IL-13-induced periostin upregulation established serum periostin as a probable biomarker of the response to anti-IL13 agents (lebrikizumab, tralokinumab) during clinical trials, although later on, serum periostin levels were considered to be not specific for severe asthma inflammation." (PMID 35887589, 2022). "Despite an increased periostin level described in children with asthma, periostin is unlikely to be a useful biomarker of type 2 inflammation in children, mainly because its levels increase due to bone growth and this may overlap with local production within the airways." (PMID 31731479, 2019). "Moreover, disease severity, percentages of patients with AERD, and airflow limitation were associated with patients with high serum TNC and periostin levels as compared with patients in the other subpopulations, suggesting that both periostin and TNC might serve as biomarkers of asthma." (PMID 30473714, 2018).
asthma (continued). "However, recent evidence demonstrated that serum periostin is not able to distinguish eosinophilic from non-eosinophilic airway inflammation, whereas blood eosinophils had the highest accuracy in the identification of sputum eosinophilia in asthma." (PMID 27965769, 2016). "A Japanese cohort of 120 patients with severe asthma showed serum CC16 was inversely correlated with sputum eosinophils and blood periostin levels, but that CC16 did not predict asthma exacerbations." (PMID 40863432, 2025). "Sputum periostin levels were detectable, and significantly highest in CRS with comorbid asthma compared to without." (PMID 36763690, 2023). "In their study, serum periostin levels were significantly higher in patients with AERD vs. ATA, in patients with severe asthma vs. non-severe, and in patients with eosinophilic vs. non-eosinophilic asthma." (PMID 37744693, 2023). "We have demonstrated, for the first time to the best of our knowledge, that periostin levels are increased in the lower airways, as examined by sputum, of patients with CRS, even when asthma does not coexist." (PMID 32015784, 2020). "There were neither significant correlations between serum periostin and TSLP levels in asthma nor IS or serum periostin and TSLP levels (or their mRNA expression) in the COPD and control groups." (PMID 33203095, 2020). "Sputum periostin levels were highest, and olfactory function was most impaired, in the CRS patients with comorbid asthma, followed by those without asthma and controls in this order." (PMID 32015784, 2020). "Other important markers which are frequently studied in asthma and COPD such as periostin, eotaxin and TSLP, though not significant, exhibited an altered profile in ACO." (PMID 32448302, 2020). "HEKs were chosen because they do not express some of the genes upregulated in asthma (CLCA1, POSTN, SERPINB2) and as such mirror expression of healthy BECs." (PMID 33362848, 2020). "Sputum periostin levels were highest in CRS patients with comorbid asthma, followed by those without asthma and healthy subjects, in this order." (PMID 32015784, 2020). "Although serum periostin has been accepted as a type 2 biomarker, serum TNC has not been evaluated as a systemic biomarker in asthma." (PMID 30473714, 2018). "Moreover, those patients with severe nonatopic asthma (including those with high FeNO as a marker of IL-13 inflammation, high eosinophils, and periostin), uncontrolled besides optimal nonpharmacological and pharmacological treatment, may benefit from omalizumab therapy." (PMID 30310816, 2018). "Periostin levels and inflammatory cells such as eosinophils and neutrophils in the lower airways are increased in patients with CRS, suggesting the presence of mutual interactions between upper and lower airways even if asthma does not coexist." (PMID 32015784, 2020). "Consistent with this hypothesis, secondary infection of IPS-1−/− mice led to a non-atopic asthma-like phenotype, including AHR, increased ASM mass, mucus hypersecretion, periostin deposition and eosinophilic inflammation." (PMID 28539639, 2017). "Recently we determined the reference ranges for serum periostin in two populations, an adult population without asthma or COPD, and an adult population with symptoms of airflow obstruction, predominantly adults with diagnosed asthma." (PMID 28194189, 2017). "Another phase 2b study of tralokinumab showed a nonsignificant reduction of the asthma exacerbation rates, and somewhat encouraging results were observed in a subgroup of patients with higher baseline levels of dipeptidyl peptidase (DPP)-4 and periostin." (PMID 29155876, 2017). "In conclusion, we have demonstrated that periostin levels and inflammatory cells such as eosinophils and neutrophils in the lower airways are increased in patients with CRS, suggesting the presence of mutual interactions between upper and lower airways even if asthma does not coexist." (PMID 32015784, 2020).
asthma (continued). "Later, Asano teams tested periostin expressions in ECRS with asthma and without asthma, respectively, and found the former showed high results compared with the latter, which indicating ECRS with other kinds inflammatory disease may significantly accelerate periostin expression." (PMID 32954441, 2021). "Because both serum periostin and TNC levels were not correlation and had different features, the combination of serum TNC and periostin levels in a multiple-marker approach might be more useful biomarkers reflecting asthma severity including airflow limitation than a single biomarker approach." (PMID 30473714, 2018).